CFTR (CF transmembrane conductance regulator)
Diseases named in the same sentence as CFTR in open-access papers (continued):
Sharing a sentence is not in itself a finding about the gene and the disease.
cystic fibrosis (continued). "A novel class of potentiator molecules was discovered on the basis of its' affinity to purified and immobilized Wt-CFTR protein and the major Cystic Fibrosis causing mutant protein, F508del-CFTR." (PMID 38982492, 2024). "For example, cystic fibrosis, a genetic disease caused by mutations in the CF transmembrane conductance regulator (CFTR) gene, is associated with low Glo1 and a GSH deficiency." (PMID 39386711, 2024). "Since the early 2000s, approximately 2,000 CFTR gene variants have been documented in the Cystic Fibrosis Mutation Database, although the full functional and pathophysiological implications of these mutations are not yet completely understood." (PMID 39296431, 2024). "The c.1585-1G>A variant is one of the ten most common CFTR variants in individuals of Northern European descent, accounting for 0.6% of the disease, and is associated with the classic cystic fibrosis phenotype." (PMID 39457459, 2024). "According to the Cystic Fibrosis Mutation Database, the p.Asn1303Lys variant is the fourth most common CFTR variant worldwide, and the Clinical and Functional Translation of CFTR (CFTR2) database reports the p.Asn1303Lys variant in more than 3300 patients." (PMID 39457459, 2024). "Cystic fibrosis is caused by pathogenic mutations in a single large gene located on human chromosome 7 which encodes the cystic fibrosis transmembrane conductance regulator (CFTR) protein." (PMID 38798310, 2024). "al assessed AlphaMissense pathogenicity predictions of missense variants in cystic fibrosis transmembrane conductance regulator (CFTR), which is heavily implicated in the development of another monogenic disease, cystic fibrosis." (PMID 38370976, 2024). "Cystic fibrosis is an autosomal recessive hereditary condition caused by a range of genetic defects in the gene coding for the cystic fibrosis transmembrane conductance regulator (CFTR) protein." (PMID 39626236, 2024). "In more than 80 % of patients it can be regarded as a minimal form of cystic fibrosis caused by biallelic CFTR pathogenic variants." (PMID 39253719, 2024). "ETI is approved in people with cystic fibrosis with one Phe508del plus a minimal or residual function mutation in CFTR (at the moment in individuals ≥ 2 years in Europe)." (PMID 38717689, 2024). "For instance, a clinical study looking into the application of CRISPR/Cas9 to target mutations in the CFTR gene, which causes cystic fibrosis." (PMID 38877530, 2024). "Cystic Fibrosis is associated with the absence or dysfunction of the CFTR protein which results in decreased epithelial Cl- secretion and ASL dehydration." (PMID 39572772, 2024). "The W1282X variant is also a Class 1 cystic fibrosis variant that prevents the creation of any CFTR." (PMID 39583120, 2024). "NCT00073463 started in 2003, aiming to test 100 participants age 12 or older for aerosolized AAV-encoded CFTR for the treatment of cystic fibrosis." (PMID 38247731, 2024). "Biallelic pathogenic variants in the CFTR gene cause cystic fibrosis, manifesting in chronic bronchopulmonary dysfunction." (PMID 39062917, 2024). "Cystic fibrosis is a recessive genetic disease caused by mutations in the gene encoding the cystic fibrosis transmembrane conductance regulator (CFTR), a selective anion channel expressed in the epithelia of various organs." (PMID 38396982, 2024). "Cystic fibrosis is a lethal genetic disease caused by variants in the epithelial anion channel cystic fibrosis transmembrane conductance regulator (CFTR)." (PMID 38271453, 2024). "A critical discovery revealed that in addition to a defective Cl- transport, CFTR mutations disrupt the transport of HCO3- in various tissues in cystic fibrosis, highlighting the pathophysiological role of impaired HCO3- secretion in cystic fibrosis." (PMID 39170739, 2024). "CFTR functional testing and the identification of two mutations linked to cystic fibrosis are additional methods of diagnosis." (PMID 38893705, 2024).
cystic fibrosis (continued). "Ivacaftor is only approved for use in the treatment of cystic fibrosis in individuals who have the particular G551D genetic mutation in their CFTR gene." (PMID 39065790, 2024). "Cystic fibrosis is a recessive genetic disease caused by mutations in the gene that codes for the cystic fibrosis transmembrane conductance regulator, CFTR." (PMID 39437760, 2024). "For example, mutations affecting the synthesis, folding, trafficking, or activity (i.e., gating or conductance) of the cystic fibrosis transmembrane conductance regulator (CFTR) all cause cystic fibrosis." (PMID 38809589, 2024). "For instance, gene therapy aims to deliver functional CFTR [Cystic Fibrosis Transmembrane Conductance Regulator] genes into affected cells in diseases such as cystic fibrosis, where mutations in the CFTR gene cause defective chloride ion transport." (PMID 38999541, 2024). "A recent study explores the use of HD-Ad combined with the CRISPR-Cas9 system for gene therapy targeting cystic fibrosis caused by mutations in the CFTR gene." (PMID 39596526, 2024). "The objective of our study was to determine the serum concentration of alpha CGRP (αCGRP) in cystic fibrosis that arises from mutations in the gene responsible for encoding the cystic fibrosis transmembrane conductance regulator (CFTR) protein." (PMID 38792587, 2024). "Cystic fibrosis is an autosomal recessive genetic disease caused by variants in the CFTR (cystic fibrosis transmembrane conductance regulator) protein." (PMID 39583120, 2024). "Cystic fibrosis is an autosomal recessive multisystem disorder caused by mutations in the cystic fibrosis conductance regulator (CFTR) anion channel." (PMID 39595943, 2024). "Cystic fibrosis is an inherited autosomal recessive disease caused by mutations in the gene encoding the cystic fibrosis transmembrane conductance regulator (CFTR), an epithelial anion channel that primarily conducts Cl− and HCO3−." (PMID 38699141, 2024). "Cystic fibrosis is a genetic disorder inherited in an autosomal recessive fashion and primarily involves loss-of-function mutations in the CFTR gene, which encodes for CF transmembrane conduction regulator (CFTR), a cAMP-regulated chloride transporter protein." (PMID 39036102, 2024). "A large number of factors, including the diversity of CFTR genotypes, modifier genes, and environmental factors, can cause significant variations in the phenotypic manifestations of cystic fibrosis in individuals." (PMID 38392563, 2024). "Infections with M. abscessus are prevalent in patients with cystic fibrosis, a genetic disease caused by a defective CF transmembrane conductance regulator (CFTR)." (PMID 38684467, 2024). "Taken together, our study underscores that there is a need for a more nuanced interpretation of CTNS mutations, revealing variable cystine transport activity for different CTNS mutations, similar to observations in cystic-fibrosis-associated CFTR mutations." (PMID 38607085, 2024). "Cystic fibrosis is a common life-threatening genetic disorder caused by mutations in the cystic fibrosis transmembrane conductance regulator (CFTR) gene." (PMID 38427726, 2024). "Cystic fibrosis is a genetic disorder caused by mutations in the cystic fibrosis transmembrane conductance regulator (CFTR) that controls chloride current." (PMID 38347907, 2024). "Cystic fibrosis is an inherited condition caused by mutations in the cystic fibrosis transmembrane conductance regulator (CFTR) gene." (PMID 39408877, 2024). "Cystic fibrosis results from pathogenetic variants in the transmembrane conductance regulator gene (CFTR MIM*602421) and appears to be clinically heterogeneous, spanning a wide phenotypic range in severity of symptoms." (PMID 38927598, 2024). "NGS analysis revealed two heterozygous mutations within the CFTR gene, known for its causative effect in cystic fibrosis." (PMID 39202455, 2024).
cystic fibrosis (continued). "Cystic fibrosis is a genetic disorder caused by mutations in the cystic fibrosis transmembrane conductance regulator (CFTR) gene." (PMID 38178983, 2023). "For instance, cystic fibrosis, the most common and fatal genetic disease in the US, has an array of clinically reported mutations in the cystic fibrosis transmembrane conductance regulator (CFTR), a chloride channel on the cell membrane." (PMID 37561577, 2023). "A relatively high number of suppressor genes have been identified for HBB and CFTR, which are mutated in sickle cell disease/β-thalassemia and cystic fibrosis patients, respectively." (PMID 37821946, 2023). "Participant 6 was homozygous for loss of the phenylalanine codon at position 508 of the CFTR gene (c.1521_1523del ΔF508), the variant most commonly associated with cystic fibrosis." (PMID 37754778, 2023). "Mutations in the CFTR gene are closely related to cystic fibrosis, and different types of CFTR mutations can lead to CFTR protein deficiency and functional impairment, and the severity of lung diseases varies significantly among different individuals." (PMID 37644544, 2023). "Cystic fibrosis is a common life-shortening genetic disease caused by mutations in the cystic fibrosis transmembrane conductance regulator (CFTR) gene." (PMID 38001937, 2023). "Cystic fibrosis is a chronic autosomal recessive genetic disease caused by a mutation in the gene responsible for the cystic fibrosis transmembrane conductance regulator gene (CFTR)." (PMID 37958017, 2023). "In case 3, cell-based NIPT was applied to test a dichorionic twin pregnancy where the fetuses were at risk of cystic fibrosis, as both parents carried NM_000492.3(CFTR):c.1521_1523del." (PMID 37829280, 2023). "As mentioned, one of the causes of FeNO reduction in patients with cystic fibrosis is the underlying CFTR dysfunction." (PMID 38053097, 2023). "Cystic Fibrosis is a life-shortening autosomal recessive genetic disorder caused by mutations in the cystic fibrosis conductance regulator (CFTR) gene." (PMID 38173934, 2023). "Cystic fibrosis is an autosomal recessive disease due to mutations in the cystic fibrosis transmembrane conductance regulator (CFTR) gene." (PMID 37374088, 2023). "Eight participants (0.93%) had a carrier status and heterozygous P/LP variants for AR diseases: CFTR cystic fibrosis, ITGB4 junctional epidermolysis bullosa type 5A, MEFV AR familial Mediterranean fever, and SLC7A9 AR cystinuria." (PMID 36635046, 2023). "As cystic fibrosis is caused by mutations in the cystic fibrosis transmembrane conductance regulator (CFTR) gene, viral vector based CFTR expression represents an attractive approach." (PMID 36992407, 2023). "Cystic fibrosis is a genetic disorder caused by a Cystic Fibrosis Transmembrane Conductance Regulator (CFTR) gene defect." (PMID 36983631, 2023). "Cystic fibrosis is a multisystem disease caused by variants causing deficient or dysfunctional CF transmembrane conductance regulator (CFTR) protein." (PMID 37047546, 2023). "Cystic fibrosis is a severe monogenic trait with autosomal recessive inheritance that is caused by mutations in the CFTR gene." (PMID 36892308, 2023). "Cystic fibrosis is characterized by impaired mucus hydration and clearance due to mutations in the CFTR gene leading to chronic pulmonary infection and (neutrophilic) inflammation." (PMID 36755071, 2023). "Cystic Fibrosis is a congenital multisystem disorder caused by mutation in the CF transmembrane conductance regulator (CFTR) gene." (PMID 36992241, 2023). "Cystic Fibrosis is a genetic disease caused by mutations in the gene encoding the Cystic Fibrosis Transmembrane Conductance Regulator (CFTR) channel." (PMID 36834620, 2023). "The authors also highlighted the crucial need for standardized diagnostic methodologies for cystic fibrosis across the Arab region, as this would lead to improvement in the detection of CFTR mutations." (PMID 36983631, 2023).
cystic fibrosis (continued). "Approximately 10% of Cystic Fibrosis patients, particularly those with CF transmembrane conductance regulator (CFTR) gene nonsense mutations, lack effective treatments." (PMID 37951948, 2023). "Cystic fibrosis is a rare and fatal disease caused by a defective mutated cystic fibrosis transmembrane regulator (CFTR) protein, an anion channel that regulates fluid secretion in glandular organs such as the lungs, pancreas, and reproductive organs." (PMID 37317269, 2023). "Cystic fibrosis is a monogenic recessive genetic disorder caused by mutations in the CF Transmembrane-conductance Regulator gene (CFTR)." (PMID 37371025, 2023). "Cystic fibrosis is an autosomal recessive disease caused by different mutations in the cystic fibrosis transmembrane conductance regulator (CFTR) gene." (PMID 36741604, 2023). "Cystic fibrosis is a recessive genetic disease thatis causedby mutations in the cystic fibrosis transmembrane conductance regulator(CFTR) protein." (PMID 37437308, 2023). "IMPORTANCE Cystic fibrosis is the most common life-limiting monogenetic disease in European populations and is caused by mutations in the CFTR gene." (PMID 36892308, 2023). "Cystic fibrosis is a life-threatening multisystem disease caused by mutations in the CF transmembrane conductance regulator (CFTR) gene." (PMID 37187291, 2023). "Cystic fibrosis is a genetic illness caused by a gene defect on chromosome 7 that encodes for CF transmembrane conductance regulator (CFTR) protein." (PMID 38111626, 2023). "A preeminent example is cystic fibrosis, an inherited disorder caused by mutations in the cystic fibrosis transmembrane conductance regulator (CFTR) gene." (PMID 37190013, 2023). "Mutations in the CFTR gene lead to Cystic Fibrosis, a lethal disease characterized by pancreatic insufficiency, increased salt concentration in sweat, male infertility, and progressive lung disease." (PMID 37371529, 2023). "Cystic fibrosis is caused by defects of the cystic fibrosis transmembrane conductance regulator (CFTR) gene." (PMID 37674160, 2023). "The severity and progression of lung disease are highly variable across individuals with cystic fibrosis and are imperfectly predicted by mutations in the human gene CFTR, lung microbiome variation or other clinical factors." (PMID 37052589, 2023). "Cystic fibrosis is the most common life-shortening inherited disease in Caucasians and is caused by variants in the CF transmembrane conductance regulator (CFTR) gene." (PMID 36832306, 2023). "Cystic fibrosis is an autosomal recessive genetic disorder caused by mutations in the CF transmembrane conductance regulator (CFTR) gene." (PMID 36712930, 2023). "More than 275 million people in the world are carriers of a heterozygous mutation of the CFTR gene, associated with cystic fibrosis, the most common autosomal recessive disease among Caucasians." (PMID 37175647, 2023). "Cystic fibrosis is a monogenic syndrome determined by over 2000 mutations in the CF Transmembrane Conductance Regulator (CFTR) gene harbored on chromosome 7." (PMID 37895314, 2023). "Cystic fibrosis is an autosomal recessive disorder arising from mutations in the cystic fibrosis transmembrane conductance regulator (CFTR) gene." (PMID 38053097, 2023). "Cystic fibrosis [CF (OMIM: #219700)] is a well-known life-limiting hereditary disease caused by deleterious mutations in the cystic fibrosis transmembrane conductance regulator (CFTR) gene on chromosome 7." (PMID 37274793, 2023). "Cystic fibrosis is an autosomal recessive disease caused by mutations in CFTR, a gene that encodes a chloride and bicarbonate channel." (PMID 37547298, 2023). "To date, more than 2000 different variants in the CFTR gene have been identified according to Clinvar database and Cystic Fibrosis Mutation Database." (PMID 37628659, 2023).
cystic fibrosis (continued). "The development of small molecules called CFTR modulators, which target the underlying molecular defects caused by mutations in the CFTR gene, has revolutionised the therapeutic approach to cystic fibrosis." (PMID 38139828, 2023). "It is well-established that individuals with cystic fibrosis, caused by biallelic germline mutations in CFTR, are at increased risk of developing colorectal cancer." (PMID 36765944, 2023). "Some evidence associates CFTR modulators with anti-inflammatory effects causing a significant reduction in sputum inflammatory markers in individuals with cystic fibrosis, including neutrophil elastase, IL-8 and IL-1beta." (PMID 37957647, 2023). "For instance, the main variant of mutation in most patients suffering from cystic fibrosis is caused by the deletion of phenylalanine at the 508th position of the CFTR protein." (PMID 37834150, 2023). "Cystic fibrosis is the most common genetic disease in Caucasians and is the result of a mutation in a gene encoding the cystic fibrosis transmembrane conductance regulator (CFTR)." (PMID 37371820, 2023). "In cystic fibrosis, deletion of phenylalanine 508(F508del)in the CF transmembrane conductance regulator (CFTR) is associatedto misfolding and defective gating of the mutant channel." (PMID 37440686, 2023). "Mutations in the CFTR gene lead to cystic fibrosis, which stands as one of the most prevalent inherited diseases among individuals of Caucasian descent." (PMID 38067172, 2023). "The CFTR anion channel is a key component of transepithelial salt-water transport in the lung, the pancreas and the intestine, and its mutations cause cystic fibrosis." (PMID 37782012, 2023). "Mutations in CFTR underlie cystic fibrosis, in which the most common mutation is deletion of a phenylalanine residue at position 508 (F508del), leading to misfolding and enhanced proteasomal degradation of the protein." (PMID 38201212, 2023). "Cystic fibrosis is a genetic disorder caused by variants in the cystic fibrosis transmembrane conductance regulator (CFTR) gene that affects approximately 90,000 people worldwide." (PMID 37686084, 2023). "Cystic fibrosis is a monogenetic disease caused by an impairment of the cystic fibrosis transmembrane conductance regulator (CFTR)." (PMID 37457734, 2023). "This includes primary ciliary dyskinesia as well as monogenic diseases such as cystic fibrosis, which is caused by a deficiency in epithelial chloride transport due to mutations in the cystic fibrosis transmembrane conductance regulator (CFTR) gene." (PMID 37109003, 2023). "Cystic fibrosis is a genetic disease caused by the presence of mutations in both copies of the gene for the cystic fibrosis transmembrane conductance regulator (CFTR) protein, which affects primarily the respiratory system and the gastrointestinal tract." (PMID 37259341, 2023). "At the germline level, two missense mutations, predicted to be likely pathogenic, of the Cystic Fibrosis gene CFTR, were found in compound heterozygosity." (PMID 37046605, 2023). "CRISPR-Cas9 also repaired the cystic fibrosis causative mutations (i.e., CFTR deletion) in human organoids cells." (PMID 37545694, 2023). "The distribution of CFTR gene mutations among male and female cystic fibrosis patients in Pakistan reveals interesting patterns." (PMID 38024076, 2023). "Ivacaftor is a highly effective drug clinically approved to treat cystic fibrosis patients carrying mutations affecting CFTR channel gating that works by increasing channel open probability." (PMID 36674751, 2023). "Cystic fibrosis is caused by mutations in the gene encoding the cystic fibrosis transmembrane conductance regulator (CFTR) channel." (PMID 37262105, 2023). "Cystic fibrosis is a genetic disease caused by mutations in the cystic fibrosis transmembrane conductance regulator (CFTR) gene, which encodes a chloride channel that regulates the balance of salt and water in secretory epithelial cells." (PMID 37274156, 2023).